BRCA1 (BRCA1 DNA repair associated)
Diseases named in the same sentence as BRCA1 in open-access papers (continued):
Sharing a sentence is not in itself a finding about the gene and the disease.
ovarian carcinoma (continued). "Recently, a significantly higher mutation burden was detected by whole genome or exome sequencing in breast and ovarian cancer with mBRCA, compared with their counterparts carrying the wild-type BRCA1 and BRCA2 (wtBRCA) genes." (PMID 24265793, 2013). "Somatic BRCA1 and BRCA2 gene alterations have been reported in sporadic epithelial ovarian cancers including loss of expression, somatic mutations, and LOH (deletions)." (PMID 23289505, 2013). "Mutational analysis of BRCA1 and BRCA2 in hereditary breast and ovarian cancer families have also been reported in several Spanish regions, showing a heterogeneous prevalence of recurrent mutations according to the geographical area." (PMID 23683081, 2013). "Still, the majority of hereditary cases, particularly those with mutations in BRCA1 and BRCA2 and, interestingly, a fraction of sporadic ovarian cancer cases with a similar phenotype, have been postulated to share “BRCAness”." (PMID 23344037, 2013). "The carriers of the BRCA1 and BRCA2 mutation have a risk of the ovarian cancer ranged 18% to 56% and 14% to 27%, respectively." (PMID 23941236, 2013). "Our understanding of the functions of BRCA1 in ovarian cancer is evolving and complicated however there is consistent evidence of a role in response to DNA damaging agents such as platinum." (PMID 22583667, 2012). "According to the literature, inherited mutations in the BRCA1 and BRCA2 tumour-suppressor genes, account for the majority of hereditary breast and ovarian cancer cases." (PMID 22923021, 2012). "Data obtained from this quantitative FST assay suggests that induction in cellular BRCA1 levels in turn stimulates extracellular FST secretion in human ovarian cancer cells." (PMID 22685544, 2012). "Novel sequence variants in BRCA1 and BRCA2 have been found in Spanish families with multiple cases of breast and ovarian cancer." (PMID 22238615, 2012). "Even though, the role of BRCA1 has been established in cases of hereditary breast and ovarian cancer, its function in ovarian surface epithelial (OSE) cells needs further assessment." (PMID 22685544, 2012). "Founder BRCA1 and BRCA2 mutations in Ashkenazi Jews in Israel: frequency and differential penetrance in ovarian cancer and in breast-ovarian cancer families." (PMID 23961350, 2012). "Mutations in the BRCA1 and BRCA2 tumor suppressor genes account for 65–85% of all hereditary ovarian cancers." (PMID 22388872, 2012). "For example, germline mutations in BRCA1, BRCA2, and Rad51D are well known to increase ovarian cancer risk." (PMID 23319948, 2012). "In the mid 1990s, a classical linkage approach identified germline mutations in two genes, BRCA1 and BRCA2, which are associated with a high risk of developing both breast and ovarian cancer." (PMID 23028338, 2012). "The first clinical study using the synthetic lethal concept was the use of PARP inhibitors in BRCA1 or BRCA2 mutated breast and ovarian cancer, which are intrinsically sensitive to PARP inhibition." (PMID 24970153, 2012). "Genetic screening of the BRCA1 and BRCA2 genes is offered to families with high risk of breast and ovarian cancer." (PMID 22350158, 2012). "Clinical geneticists use the BWA to calculate BRCA1 and BRCA2 mutation carrier probabilities and breast/ovarian cancer risks." (PMID 22490389, 2012). "Another two studies demonstrated that BRCA1 and BRCA2 mutations represent 10–15% of all ovarian cancers." (PMID 22187038, 2012). "We describe here the results of BRCA1/BRCA2 germline analysis in an Argentinean series of breast/ovarian cancer patients selected for young age at diagnosis or breast/ovarian cancer family history." (PMID 23961350, 2012). "A recent population-based study showed a combined BRCA1 and BRCA2 mutation frequency of 13.3% among 1,342 women with ovarian cancer." (PMID 22388872, 2012). "Currently, we know that a woman who inherits a fault in one of two genes, BRCA1 or BRCA2, has a high risk of developing both breast and ovarian cancer." (PMID 23028338, 2012).
ovarian carcinoma (continued). "Known mutations in BRCA1/2 and MMR genes can only explain a small part of the familial aggregation of ovarian cancer." (PMID 23133607, 2012). "Meta-analyses have revealed a wide variance in cumulative ovarian cancer risk for BRCA mutation carriers, on average 40% in BRCA1 versus 11-18% in BRCA2 mutation carriers." (PMID 23039163, 2012). "Clinical geneticists use the BWA to calculate BRCA1 and BRCA2 mutation carrier probabilities and breast/ovarian cancer risks, which are used to determine eligibility for genetic testing or to provide individually tailored clinical management." (PMID 22490389, 2012). "Mutations of the genes BRCA1 and BRCA2 are associated with a high lifetime risk of developing breast and/or ovarian cancer." (PMID 22187038, 2012). "The molecular therapeutic targeting paradigm and the concept of synthetic lethality as exemplified by BRCA1/2 mutations and PARP inhibition offer profound opportunities for ovarian cancer drug development and discovery." (PMID 22481932, 2012). "For women with a personal or family history of breast and/or ovarian cancer, BRCA1/2 full-sequencing and analysis for large genomic rearrangements (LGR) are routinely used to quantify the genetic component of cancer risk." (PMID 22713736, 2012). "As 20% of high grade serous sporadic ovarian carcinomas have BRCA1 and BRCA2 mutations, the role of HR in ovarian cancer has been well established." (PMID 22253870, 2012). "Our microarray results suggest that BRCA1 selectively modulates SMAD6 expression in ovarian cancer cells." (PMID 22685544, 2012). "In a genomic analysis of high-grade ovarian cancer, 11% of BRCA1 silencing was the result of hypermethylation and epigenetic modification rather than mutations." (PMID 22235203, 2012). "We performed microarray analysis on human ovarian carcinoma cell line SKOV3 that stably overexpress wild-type BRCA1 and compared with the corresponding empty vector-transfected clones." (PMID 22685544, 2012). "The BWA returns BRCA1 and BRCA2 mutation carrier probabilities and age specific breast/ovarian cancer risks in a 'Computed Results' Web page." (PMID 22490389, 2012). "Eighteen patients (14 BRCA1; 4 BRCA2; age range 37–73 years, median 58) have developed ovarian cancer after receiving their positive mutation test results." (PMID 22187038, 2012). "PARP inhibitors have demonstrated promising results in patients with BRCA1- or BRCA2-positive ovarian cancer." (PMID 22253870, 2012). "BRCA1 (tumor suppressor) plays critical roles in DNA repair, cell cycle checkpoint control and maintenance of genomic stability in human breast and ovarian cancer." (PMID 22227970, 2012). "BRCA1 is associated with a 40% lifetime risk of ovarian cancer, and BRCA 2 has an approximately 15% lifetime risk of ovarian cancer." (PMID 22235203, 2012). "Additionally, screening for germline mutations in BRCA1/BRCA2 is also a promising method for early detection of ovarian cancer in current clinical practice since high risk populations with corresponding mutations could be genetically predisposed toward developing cancer." (PMID 23319948, 2012). "Genes rearranged in ovarian cancer are highly linked to vital genes like MYC, BRCA1, and PAX6 that were also altered in ovarian cancer." (PMID 22811706, 2012). "Women with inherited mutations in BRCA1 on chromosome 17q21 or BRCA2 on chromosome 13q31 are at significantly higher risk of developing breast and ovarian cancer than women in the control population." (PMID 22330607, 2012). "Numerous studies demonstrate that mutations in BRCA1 or BRCA2 can predispose one to breast and ovarian cancer, among other cancers." (PMID 22962582, 2012). "An analysis of 70 tumours from patients with sporadic ovarian cancer for BRCA1 mRNA expression correlated low BRCA1 mRNA expression with improved survival following platinum-based chemotherapy." (PMID 22312502, 2011).
ovarian carcinoma (continued). "In a study of ovarian cancer, of 115 primary sporadic ovarian carcinomas, 39 (34%) had low BRCA1 protein and 49 (42%) had low BRCA2 expression." (PMID 24212667, 2011). "Women with a known BRCA1 or BRCA2 mutation should be offered prophylactic mastectomy and bilateral salpingo-oophorectomy (BSO) in order to decrease the risk of breast and ovarian cancer." (PMID 22312502, 2011). "For example, the probability of carrying a germline mutation in BRCA1 or BRCA2 is low unless a woman has a very strong family history of breast and/or ovarian cancer." (PMID 21352566, 2011). "Antisense inhibition of BRCA1 expression in the cisplatin-resistant clone of SKOV3 ovarian cancer cell line restored sensitivity to the drug." (PMID 21819606, 2011). "Mutations in BRCA1 and BRCA2 were found, respectively, in nine and three percent of breast and ovarian cancer patients." (PMID 21559243, 2011). "Individuals who carry an inherited mutation in the breast cancer 1 (BRCA1) and BRCA2 genes have a significant risk of developing breast and ovarian cancer over the course of their lifetime." (PMID 22312502, 2011). "Germline mutations of the BRCA1 and BRCA2 genes represent the most significant and thus far the best characterized genetic risk factors for breast and ovarian cancer development." (PMID 22032251, 2011). "These preclinical data serve as proof-of-concept for synthetic lethality in BRCA-deficient cell lines and provide important rationale for studying PARP inhibitors in patients with BRCA1/2-asssociated breast and ovarian cancer." (PMID 21504625, 2011). "Several likely pathogenic RAD51C mutations have been identified in BRCA1- and BRCA2-negative breast and ovarian cancer families." (PMID 21980511, 2011). "Incidence of BRCA1 or BRCA2 mutations among different sub-groups of Slovenian families with breast and ovarian cancer." (PMID 21232165, 2011). "Case report on a BRCA1-related ovarian cancer relapsed after prolonged post-surgical paclitaxel-carboplatin therapy; each of 4 consequent relapses showed complete response to paclitaxel-cisplatin combination." (PMID 21819606, 2011). "Up to now, several comprehensive studies performed throughout Europe determined the mutation profiles of BRCA1 and BRCA2 in families with history of breast and ovarian cancer." (PMID 21232165, 2011). "In the most comprehensive of these studies, the authors identified 26 BRCA mutations (15 BRCA1 and 11 BRCA2) in 287 Greek breast/ovarian cancer families using dHPLC followed by direct sequencing." (PMID 22085629, 2011). "The BRCA1/2 genes account for a significant portion of hereditary breast and ovarian cancers and they are especially prevalent in the Ashkenazi Jewish population." (PMID 21711529, 2011). "As far as we know, there are only two Hereditary Breast and Ovarian Cancer families with LGRs including a whole-gene BRCA1 deletion reported to date." (PMID 21989022, 2011). "Germline mutations in either of the two tumor-suppressor genes, BRCA1 and BRCA2, account for a significant proportion of hereditary breast and ovarian cancer cases." (PMID 21989022, 2011). "Previous analysis of the protein showed that PP1α dephosphorylates the BRCA1 protein, coded by the tumour suppressor BRCA1, in breast and ovarian cancer." (PMID 21847129, 2011). "Research into the hereditary breast and ovarian cancer genes, breast cancer 1 (BRCA1) and BRCA2, is an area of ongoing discovery in the molecular biology of cancer." (PMID 22312502, 2011). "Different mutations in BRCA1 and BRCA2 genes have a different penetrance for breast and for ovarian cancer." (PMID 21232165, 2011). "In general, the mutation detection rates for BRCA1 and BRCA2 genes in the members of Slovenian families with breast and/or ovarian cancer are comparable with the mutation frequencies in these two genes reported for other countries." (PMID 21232165, 2011). "Hypermethylated BRCA1 gene has diminished expression values, ranging from 12% to 16% among epithelial ovarian cancers." (PMID 21577260, 2011).
ovarian carcinoma (continued). "Meanwhile, hypermethylation of BRCA1 is found primarily in breast and ovarian cancer with an average maximum probability of 0.84 and approximately 41 evidence sentences." (PMID 22168213, 2011). "The inactivation of BRCA1 is a relatively frequent event in sporadic ovarian cancer and has been shown to occur through a number of epigenetic mechanisms such as promoter hypermethylation and loss of heterozygosity." (PMID 22312502, 2011). "The BRCA1 and BRCA2 genes were found to be mutated in a large number of families with multiple cases of an early onset of breast and ovarian cancer." (PMID 21232165, 2011). "Recent studies with BRCA1, however, have noted a promising role in determining clinical outcome for ovarian cancer patients." (PMID 21577260, 2011). "Mutations in BRCA1 and BRCA2 are highly penetrant and confer an increased risk of breast and ovarian cancer in carriers." (PMID 21232165, 2011). "Some of the patients had the ovaries removed because they were carriers of a mutation in BRCA1 or BRCA2, which sets them at high risk to develop ovarian cancer." (PMID 21785733, 2011). "Specifically, ovarian cancers frequently exhibit “BRCAness” due to defects in BRCA1 or BRCA2, or other ill-defined changes that disrupt the homologous recombination DNA repair pathway." (PMID 22194930, 2011). "To further investigate the role of RAD51C as an HBOC predisposition gene, we performed complete sequencing of RAD51C to screen for mutations in 286 BRCA1- and BRCA2-negative breast and/or ovarian cancer cases with a family history of breast and ovarian cancer." (PMID 21980511, 2011). "The identification of BRCA1 and BRCA2 gene mutations and their relationship to ovarian cancer has resulted in an awareness of family history in many women with ovarian cancer." (PMID 22112691, 2011). "While it is well known that use of this model produces estimates of the probability a women carries a BRCA1 or BRCA2 mutation, it also estimates of risks of breast and ovarian cancers based on the genetic, personal and family history data provided by the user." (PMID 21352566, 2011). "For example, a woman who carries specific mutations in the BRCA1 or BRCA2 (BReast CAncer) genes has a much higher risk for breast and ovarian cancer over her lifetime than the general population." (PMID 22047175, 2011). "When comparing the study groups, the highest mutation detection rate in Slovenian population was observed in the families with at least one breast and at least one ovarian cancer (Group B) - 42% for BRCA1 and 8% for BRCA2 or 50% for both genes." (PMID 21232165, 2011). "For example, LOH is a frequent event for BRCA1 in breast and ovarian cancers, for MSH3 in breast, bladder and non-small cell lung cancers, and for PDGFRL in sporadic hepatocellular carcinomas, colorectal and non-small cell lung cancers." (PMID 21108794, 2010). "Women who have inherited mutations in the BRCA1 or BRCA2 genes have substantially elevated risks of breast and ovarian cancer." (PMID 20961453, 2010). "As a result of these promising findings, there are currently several PARPi in various stages of clinical development for use in patients with BRCA1/2-mutant breast and ovarian cancers." (PMID 20182637, 2010). "Defining how BRCA1 participates in the DNA damage response is of a major importance not only for understanding breast and ovarian cancer development, but also towards helping to improve current cancer therapeutic protocols." (PMID 21103343, 2010).
ovarian carcinoma (continued). "In a retrospective cohort of 70 sporadic epithelial ovarian cancer patients treated with platinum-based chemotherapy, those with low levels of BRCA1 mRNA expression had a significantly improved survival in comparison with those with high levels." (PMID 20209131, 2010). "The ovarian cancer SIR was 12.38 (3.1–49.51) for BRCA1 and the prostate cancer SIR was 18.55 (4.64–74.17) for BRCA2." (PMID 20877337, 2010). "In case of the ovarian carcinoma cell lines OVCAR-5, OVCAR-4 and NCI/ADR-RES, the methylation status of CGIs associated with the genes ABCB1, BRCA1, CDH1, DNAJC15, and SULF2 was connected to the expression of the genes." (PMID 20544021, 2010). "Our group has shown that the treatment of A2780s/cp ovarian cancer cells with the TSA analogue, M344, causes the downregulation of BRCA1 mRNA and protein levels." (PMID 20182637, 2010). "In this respect, data obtained in primary cells and in breast and ovarian cancer cell lines has shown that AKT1 represses BRCA1 foci formation." (PMID 21203397, 2010). "Another group used both BG-1 and OVCAR5 ovarian cancer cell lines that were either stably transfected with a BRCA1 antisense construct or transiently transfected with a siRNA against BRCA1." (PMID 20182637, 2010). "The results of the Phase II trial, presented at ASCO 2009, primarily aimed to test the efficacy of olaparib in confirmed BRCA1/BRCA2 carriers with advanced chemotherapy-refractory ovarian cancer." (PMID 24281034, 2010). "LOH and copy number abnormalities are often associated with BRCA1, and BRCA2-associated breast or ovarian cancer." (PMID 20877358, 2010). "Here we found that phosphorylation of STAT1, as well as STAT4 and STAT6 (not shown) were simultaneously activated by PAF treatment in BRCA1-mutant ovarian cancer cells (UWB1)." (PMID 20576130, 2010). "Based on the current knowledge, it is reasonable to recommend prophylactic oophorectomy for BRCA1 or BRCA2 mutation carriers when childbearing is completed in order to reduce the risk of developing breast and ovarian cancer." (PMID 20961453, 2010). "Germline mutations in the high penetrance genes BRCA1 and BRCA2 are responsible for the vast majority of families containing multiple cases of ovarian cancer (>3 cases) and two or more cases of breast and ovarian cancer." (PMID 19543528, 2009). "Breast and ovarian carcinomas in BRCA1 or BRCA2 mutation carriers usually have somatic deletions of the wildtype allele, rendering the neoplasm BRCA1 or BRCA2 deficient." (PMID 19602291, 2009). "Germline mutations in BRCA1 were often seen in the two regions, suggesting that the RING finger and BRCT motifs play an important role in the development of breast and ovarian cancers." (PMID 19768112, 2009). "The precise identification of germline BRCA1 and BRCA2 mutations is a major concern for geneticists counseling families with a high risk of breast and ovarian cancers." (PMID 21637503, 2009). "BRCA1 promoter methylation occurs in 5–20% of sporadic ovarian carcinomas, while BRCA2 methylation is rare." (PMID 19602291, 2009). "BRCA1 and BRCA2 were originally identified based on genetic linkage to families with an increased risk of breast and ovarian cancer." (PMID 20046879, 2009). "This study indicates that BRCA1/2 related ovarian cancers have a better outcome because are intrinsically highly sensitive to platinum containing chemotherapy." (PMID 19825178, 2009). "The identification of BRCA1/2 related ovarian cancer as a distinct disease has important implications." (PMID 19825178, 2009). "High grade serous ovarian carcinomas, the most common and lethal subtype of ovarian cancer, can occur sporadically or in the setting of BRCA1/2 syndromes." (PMID 19798417, 2009).